CRACDL (CRACD like)
Synonyms: C2orf55; KIAA1211L; MGC42367
Tractability: PROTAC: ubiquitination databases record sites on it.
Gene: Protein-coding gene on chromosome 2 (98,793,845 to 98,936,259, reverse strand). Ensembl gene ENSG00000196872.
Subcellular location (Human Protein Atlas): Centrosome; Microtubules; Cytokinetic bridge
Genetic constraint (gnomAD): Loss-of-function variants: 25 observed, 55.96 expected, observed/expected ratio (o/e) 0.45, 90% interval 0.32 to 0.62. The synonymous counts are far from expectation, so gnomAD's model fits this gene poorly and the ratio says little. Missense variants: 1,272 observed, 1,148.3 expected, observed/expected ratio (o/e) 1.11, 90% interval 1.06 to 1.16. Synonymous variants: 616 observed, 507.02 expected, observed/expected ratio (o/e) 1.21, 90% interval 1.14 to 1.3.
Homologues: Orthologues: chimpanzee CRACDL (99% identical), macaque CRACDL (94% identical), rabbit CRACDL (69% identical), dog CRACDL (64% identical), pig CRACDL (64% identical), mouse Cracdl (63% identical), rat Cracdl (62% identical), tropical clawed frog cracdl (29% identical). Paralogues in human: DNAAF3 (8% identical).
Diseases named in the same sentence as CRACDL in open-access papers:
CRACDL is named in the same sentence as 5 diseases in open-access papers, as found by Europe PMC text mining. Sharing a sentence is not in itself a finding about the gene and the disease.
CRACDL shares sentences with these, for which no sentence is quoted: paranoid schizophrenia (2 papers); psychiatric disorder (2); bipolar disorder (1); Intellectual disability (1); opioid use disorder (1).